CD4 (CD4 molecule)
Diseases named in the same sentence as CD4 in open-access papers (continued):
Sharing a sentence is not in itself a finding about the gene and the disease.
melanoma (continued). "Deeper knowledge of the behavior of CD4+T-cells holds vast potential in guiding future cellular anti-melanoma treatments." (PMID 40226614, 2025). "We had previously reported that CD4+ T cell depletion suppressed the growth of mock tumors in a B16F10 melanoma model, whereas this effect was lost in tumors expressing ULBP2." (PMID 40558520, 2025). "In cancer, cytotoxic CD4+ T cells have been implicated in tumor killing after CTLA-4 blockade in lymphopenic murine hosts and in patients with melanoma after ipilimumab." (PMID 40299576, 2025). "In early adoptive T cell transfer experiments, transfer of CD4+CD25-Th cells with tumor/self-reactive CD8+ T cells into CD4+ T cell-deficient hosts induced autoimmunity and regression of established melanoma." (PMID 41256311, 2025). "Melanoma vaccines deliver immunogenic antigens for presentation by MHC I or MHC II molecules to CD8+ or CD4+ T cells, respectively." (PMID 40006740, 2025). "Based on IHC identification of T lymphocytes via CD3 staining, we analyzed the proportions of CD8+ and CD4+ lymphocytes in TILs across all primary melanomas in this study." (PMID 39976551, 2025). "When administered by intratumoral injection in B16-F10 melanoma and 4T1 breast tumor models in mice, it suppressed tumor growth and increased the activation of M1 macrophages, dendritic cells, and CD4+/CD8+ T cells." (PMID 41303564, 2025). "It is currently approved for lung cancer vaccines and, when combined with peptide vaccines, enhances CD8 + and CD4 + T cell infiltration, as observed in melanoma studies." (PMID 39789208, 2025). "The understanding of how T helper subsets impact tumor formation has primarily come from in vivo mouse models, whereby B16 melanomas have been demonstrated to be eradicated by CD4+ TH1 and TH2 cells." (PMID 39712007, 2024). "Very little research has used IHC or IF to examine the predictive significance of CD4+ TIL enumeration in melanoma." (PMID 39712007, 2024). "Research has shown that reduced expression of the nuclear factor erythroid 2-related factor 2 (NRF2) signaling pathway can significantly increase infiltration of CD8+ and CD4+ T cell into tumors, inhibit melanoma growth, and decrease PD-L1 expression." (PMID 39660124, 2024). "In tumors treated with in vivo reprogramming, we observed a large cluster of cytotoxic CD4+ T cells that has been described to harbor the capacity to directly eradicate melanoma cells." (PMID 39236156, 2024). "Of these cells, TNBC, BCC, and melanoma comprised the largest proportion; only B cells, CD4+ T cells, CD8+ T cells, Tregs, and macrophages were shared by the five cohorts, showing that they are typically present in tumor tissues." (PMID 38569519, 2024). "Naïve CD4+ T cells can further differentiate into CD4+ CTLs and mediate the killing of melanoma cells in lymphocytopenic host bodies." (PMID 38515134, 2024). "CD4+ T cells co-cultured with B16F10/shDRG2 melanoma cells produced significantly higher levels of IL-2 than those co-cultured with B16F10/pLKO." (PMID 38802348, 2024). "On the other hand, TNF administration in the murine melanoma metastatic model increased metastasis and correlated with the infiltration of regulatory CD4(+)/Foxp3(+) T cells in the lungs." (PMID 39650654, 2024). "Immune cell infiltration analysis demonstrated enrichment of CD4+ naïve and memory T cells, macrophages (M0 and M2), and CD8+ T cells in melanoma, all of which were associated with the expression of the four feature genes." (PMID 39835132, 2024). "Data-based simulations revealed that high levels of E2F1 in melanoma cells trigger autoactivation and a paracrine positive feedback loop with CD4+ T cells via secretion of IL-6 to the tumor niche to generate an inflammatory secretome." (PMID 39544930, 2024). "The frequency and number of activated CD4+IFNγ+ TH cells isolated from B16 melanomas was similar in Foxp3GFP-Fth∆/∆ vs. control Foxp3GFP mice (Fig. EV5F)." (PMID 38499786, 2024).
melanoma (continued). "PGE2 directly inhibits the proliferation and effector functions of CD4+ and CD8+ T cells and promotes their differentiation in regulatory T cells (Tregs), contributing to the immune response associated with melanoma." (PMID 39450252, 2024). "Here, we show that the modulation of CD4+FOXP3+CD25+regulatory T (Treg) cells upon anti-CTLA4 treatment protects against lymphedema development in patients with melanoma and in a mouse lymphedema model." (PMID 39737964, 2024). "Conversely, in cases of superficial spreading melanoma, the classic predominance of CD4+ cells persists, respectively, in cases with low H-score expression." (PMID 38673920, 2024). "Previous studies have linked decreased frequencies of Ki67+ Eomes+ CD4+ T cells with irAE, while increased levels of Ki67+ PD1+ CD8+ T cells are linked to prolonged progression-free survival in melanoma patients treated with anti-PD-1 therapy." (PMID 38254759, 2024). "Further, studies in both preclinical models and human melanoma patients have revealed that anti-CTLA-4 induces ICOS+ CD4 T cells expressing IFN-γ78,79." (PMID 38187708, 2024). "Nonetheless, in both melanoma models the ratio of pro-inflammatory CD4+ T helper cells to Tregs was increased, implying that in vivo cDC1 reprogramming drives a potent CD4+ T cell response." (PMID 39236156, 2024). "Another example of miRNAs’ functions in the TME is the miRNA-17-92 cluster, whose deficiency in CD4+ T cells leads to impaired response of Th1 cells towards B16 melanoma tumor cells and turns off CD4+ T cells cooperation with CD8+ T cells." (PMID 39195233, 2024). "The frequency of circulating CD4+CD26-high T lymphocytes is a potential biomarker since it is associated with clinical outcomes (and at least with survival in melanoma patients)." (PMID 39001488, 2024). "All melanoma patients had reduced CD4+CD26-high T cell frequencies compared to healthy subjects, while low baseline percentages of CD4+CD26-high T cells were associated with worse clinical outcomes." (PMID 39001488, 2024). "In persons with melanoma, higher levels of Ruminococcaceae in the gut correlated with increased circulating effector CD4+ and CD8+ T cells and higher infiltrating antitumor immune cells, as well as a maintained cytokine response to anti-PD1 therapy." (PMID 38942995, 2024). "Another notable advance in solid tumors, such as melanoma, has been the characterization of a subset of tumor-infiltrating CD4+ T cells that express the FcγRI receptor." (PMID 39091493, 2024). "IL-6 expression, driven by a newly identified interaction between endogenous E2F1 and active STAT3, leads to massive cytokine secretion via a positive feedback loop, both in melanoma and CD4+ T cells." (PMID 39544930, 2024). "LTBR-ig-mediated suppression of the expansion and activity of PDPN LNSCs significantly reduces melanoma tumor growth and promotes the infiltration and proliferation of CD4 TILs." (PMID 38175686, 2024). "In vivo murine models, CD4+ Th1 and Th2 cells have been shown to efficiently eliminate B16 melanomas." (PMID 39273452, 2024). "Previous research has demonstrated that CD4+ T cells can be found in the tumour microenvironments of lung cancer, melanoma, CRC, lymphomas, cervical cancer and ovarian cancer, but the role of CD4+ T cells in EC is relatively understudied." (PMID 39816386, 2024). "Although clinical data on CD4+ T cells in immunotherapy are limited, the therapeutic potential of CD4+ T cells has been demonstrated in cholangiocarcinoma and melanoma." (PMID 39106430, 2024). "Melanoma patients classified with a low-risk score based on the ITRGM signature exhibit extensive infiltration of immune cells, notably CD4+ T cells, M1-polarized macrophages, CD8+ T cells, NK cells, and B cells." (PMID 39355255, 2024). "It is widely recognized that BRAFV600E in melanoma can act as an immunogenic peptide when presented on MHC-II by CD4+ T-cells." (PMID 39061208, 2024).
melanoma (continued). "In patients with liver metastasis of melanoma, an increase in the levels of extracellular collagen deposition is associated with reduced tumor infiltration by CD8+ T cells, CD4+ T cells, macrophages, and NK cells." (PMID 39845977, 2024). "CD4+ T cells kill melanoma cells in an MHCII-restricted manner after overt treatment with antigen-specific CD4+ T cells." (PMID 38515134, 2024). "Melanoma antigens presented to CD4+ T cells by Class II MHC were identified later than the Class I associated antigens, and even now, algorithms for predicting epitopes for CD4+ T cells lag behind those for CD8+ T cells." (PMID 38519525, 2024). "By contrast, melanoma-derived CCL21 attracts CCR6+ (CD4+) ILC3, which interacts with fibroblastic reticular cells (FRC) to form lymphoid-like stroma, creating a tolerogenic tumor environment." (PMID 39126091, 2024). "In contrast to monocultured CD8+ or CD4+ T cells, metastatic melanoma cells showed a high IL-6 concentration in the supernatant." (PMID 39544930, 2024). "The identified cell types were CD8+ T cells, CD4+ T cells, NK cells, B cells, macrophages, and melanoma cells." (PMID 38942020, 2024). "Previous research has shown that central memory CD4+ T cells in peripheral blood can be used as predictors of PD-1 blockade therapy in patients with malignant melanoma." (PMID 38231411, 2024). "The precise role of how CD4+ T cell sub-populations influence the growth of tumors and immune evasion remain to be defined in melanoma patients with ITM." (PMID 38673829, 2024). "Subsequently, a vaccine was developed comprising six melanoma peptides presented by class II HLA-DR molecules, whose injection induced CD4+ T-cell responses in most melanoma patients and induced a clinical response in some patients." (PMID 39727691, 2024). "In Frankel’s work relying on tyrosinase expressing-melanoma models, unsorted, CD4+ and CD8+ TCR-T cells exert cytotoxic activity against cognate target tumor cell line, both in vitro and in vivo." (PMID 38545119, 2024). "We used high-E2F1 vs. E2F1-KD melanoma cell lines grown as monocultures or together with either CD4+ or CD8+ T cells from healthy donors." (PMID 39544930, 2024). "The populations of infiltrating CD8+ and CD4+ T cells were increased to a small extent in the TILs of BRafV600E/Ptennull/Mi-2βnull melanoma." (PMID 38461299, 2024). "Of note, the expression of KYNU (encoding kynureninase, a key enzyme in the kynurenine metabolic pathway involved in immune response) has been correlated with CD4 T cell state in the melanoma microenvironment." (PMID 38334658, 2024). "Administration of CXCL10-Fc and CXCL9-Fc limits melanoma growth while selecting subtypes of effector and cytotoxic CD4+ and CD8+ T cells with an IFN-γhigh signature, further limiting tumor growth." (PMID 39474427, 2024). "Although higher Treg presence in melanoma patients is generally associated with a poor prognosis, the effect of ICI treatment on this CD4+ subtype appears to differ between anti-CTLA-4 and anti-PD-1." (PMID 39273452, 2024). "In subsequent investigations, the research team discovered three HLA‐DRB40101−0103 MHC class II epitopes, recognised by CD4+ T lymphocytes in two melanoma patients." (PMID 39275923, 2024). "Predominant CD4 + T cells in the TILs was reported for breast cancer (76%), with lower levels in gastrointestinal cancers (54%) and malignant melanoma (21%)." (PMID 38630265, 2024). "Although OX-40 expression and its role in NK cells have been minimally investigated, it has been detected in CD4+ TILs in breast cancer, sarcoma, melanoma, and colorectal cancer." (PMID 39201462, 2024). "Maraviroc, another anti-retroviral drug that antagonizes CCR5, improved immune responses in melanoma by increasing CD4 + and CD8 + T cell infiltration and remodeling the tumor microenvironment." (PMID 39609320, 2024).
melanoma (continued). "We investigated the immunomodulatory properties of the E2F1-induced melanoma secretome in an indirect coculture system with healthy donor-derived CD4+ and CD8+ T cells." (PMID 39544930, 2024). "In our melanoma dataset, we show that using CD4+ TEM frequencies to predict hepatitis after immune checkpoint inhibitor (ICI) therapy leads to a right-skewed ROC curve." (PMID 38926389, 2024). "We created different versions of the model to represent the regulation of the pathway in melanoma and CD4+ T cells." (PMID 39544930, 2024). "Foxp3-DTR-KI mice treated with diphtheria toxin also suppressed B16F10 melanoma growth, indicating that selective Treg depletion mimicked total CD4 T cell depletion effects." (PMID 39470607, 2024). "Further analyses showed that CLEC2D expression increases in peripheral blood CD4+ T cells in long-term survivor melanoma patients after vaccination." (PMID 38675738, 2024). "Based on the expression of Granzymes, Perforin, Granulysin and other cytolysis-associated markers, CD4+ CTL have been detected in bladder cancer, colorectal cancer, lung cancer, melanoma, and other tumors." (PMID 37965314, 2023). "By detecting HLA I-restricted tumor-related antigens and HLA II-restricted neoantigens, melanoma cells can directly activate depleted cytotoxic CD4+T cells." (PMID 36891324, 2023). "A recent study in the MeLiM pig model showed that CD4−CD8+ T cells accounted for the majority of tumor-infiltrating lymphocytes (TILs) during late phases of melanoma regression and that only CD4+CD8hi TILs expanded during latest stages." (PMID 37526660, 2023). "In melanoma, CD4+ T cells can also activate CD8+ T cells to differentiate into cytotoxic T lymphocytes (CTLs), while maintaining and boosting the antitumor responses of CTLs." (PMID 37388230, 2023). "Direct CD4+ T cell recognition of melanoma cell lines expressing MHC-II naturally or after CIITA transduction has been reported in 2 studies." (PMID 36512410, 2023). "In advanced melanoma murine models, development of a tumor reactive CD4+ T cell population with cytotoxic activity have been identified, indicating that CD4+ cells can obtain cytotoxic functions." (PMID 37122741, 2023). "Reciprocally, treatment of PBMC from patients with NSCLC, HNSCC, and melanoma with feladilimab upregulated PD-1 expression on CD4+ and CD8+ T cells." (PMID 37593752, 2023). "Of note, the median frequencies of the CD4+ T cell expressing CD26high were significantly less in melanoma patients than in the healthy group (p = 0.001)." (PMID 37170241, 2023). "Despite an overall increase in T cell infiltration, human melanoma with high levels of INHBA had a two-fold lower CD8 to CD4 ratio." (PMID 38304252, 2023). "Tumor-bearing lymphopenic mice received adoptive therapy with CD4+ T cells expressing a transgenic T cell receptor (tgTCR) specific for the melanoma antigen TRP-1." (PMID 37965314, 2023). "Independently, a CD4+ T-cell clone derived from a melanoma patient with disease regression was found to recognise an EphA3 epitope and to induce a preferential immune response against melanoma cells." (PMID 36830852, 2023). "While we did not detect significant associations between metabolic parameters and melanoma antigen-specific T-cell responses, increased mitochondrial and FAO dependence showed a trend towards increased T-cell responses in CD8 and CD4 T cells respectively." (PMID 37938561, 2023). "Early studies have found that in the melanoma context, metastatic lymph nodes were infiltrated not only by T cells (CD4+, CD8+, and Tregs) but also by a substantial percentage of NKT and NK cells that express LAG-3." (PMID 37670328, 2023). "The results display both an increased CD8+ and CD4+ T cell immune response against E7-expressing melanoma B16 cells, with increased survival compared to the control group." (PMID 37513985, 2023).
melanoma (continued). "It is important to note that silencing TIM-3 enhanced the immune function of CD4+ T cells and inhibited M2 macrophage polarisation, attenuating the growth and metastasis of melanoma cells." (PMID 36980583, 2023). "Evidence of antitumor activity of neoantigen specific CD4+ T cell has been reported in different tumor types including breast cancer, melanoma, pancreatic cancer." (PMID 37287989, 2023). "There is evidence for a baseline TERT-specific CD4+ T cell immune response, occurring in over 50% of melanoma patients, rising to 80% in ICI responders." (PMID 37418389, 2023). "CIRT has currently been investigated in melanoma in combination with anti-PD-1 therapy and was shown to enhance CD4+ and CD8+ tumor infiltration." (PMID 37626741, 2023). "In patients with melanoma, the relative median percentages were 22.40 [16.95; 37.15] for CD4+CD26neg, 69.50 [58.70; 75.55] for CD4+CD26int, and 7.30 [4.70; 10.90] for CD4+CD26high." (PMID 37170241, 2023). "As reported, the median percentages of CD4+ CD26neg T cells, which possess immunosuppressive properties, were elevated in melanoma subjects as compared with healthy individuals (p = 0.029)." (PMID 37170241, 2023). "Nonetheless, treatment of B16 melanoma tumors with NDV in vivo leads to an increase in infiltrating CD4+ and CD8+ T cells that are activated and highly proliferative." (PMID 37974615, 2023). "Another study indicated that immunization of mice with citrullinated vimentin peptides resulted in anti-tumour effects against subcutaneous B16 melanoma, inducing a CD4+ T-cell response and resulting in an approximate 80% survival rate." (PMID 37778382, 2023). "NY-ESO-1 antigen-specific CD4+ T cells directly lysed autologous melanoma cells, and their responses were enhanced after ipilimumab treatment." (PMID 38328405, 2023). "In contrast, in adoptive transfer model bearing melanoma, Gzmb+CD4+ T cells generated under the additional use of anti‐OX40 agonists (OX86) and cyclophosphamide (CTX) were also Eomes+." (PMID 37829505, 2023). "Specifically, fucosylation regulates the cell surface abundance of HLA-DRB1, which triggers robust CD4+ T cell-mediated itIC induction and melanoma suppression." (PMID 36690875, 2023). "Examination of cluster-specific gene markers revealed 16 distinct cell subtypes, including 3 myeloids, 2 NK cells, 2 CD8 T cells, 3 CD4 T cells, 2 cycling lymphocytes, 1 B cell, and 3 melanoma cell clusters." (PMID 37487666, 2023). "Expression of SELPLG (P selectin ligand) in the TME is correlated with increased melanoma infiltration by B cells, CD4+ and CD8+ T cells, DCs, and macrophages." (PMID 37435077, 2023). "were the first to described cytolysis of human melanoma cells by NY-ESO-specific CD4+ T cells, that they found induced or enhanced in peripheral blood of patients treated with the anti-CTLA-4 blocking antibody ipilimumab." (PMID 37965314, 2023). "For example, a dual inhibitor of histone and DNA methyltransferases was shown to induce apoptosis in B16-F10 melanoma and subsequently resulted in increased activation of CD4+ and CD8+ T-cells within the TIME and tumor growth delay." (PMID 37626741, 2023). "In line with this regulation, patient-derived JAK1/2-deficient melanoma cells displayed a stable MHC Class II-negative phenotype, resistant to CD4+ CTL." (PMID 37965314, 2023). "So far, CD4+ T cell-mediated killing of either MHC Class II-matched or autologous tumor cells has been demonstrated in melanoma, bladder cancer and glioblastoma." (PMID 37965314, 2023). "Direct cytotoxicity of CD4+ CTLs against tumor cells was initially reported in melanoma patients treated with ipilimumab, a monoclonal antibody targeting CTLA-4." (PMID 38077321, 2023). "In vitro, CD4+ T cells derived from the sTS3 T cell clone had increased proliferative capabilities when co-cultured with its autologous SMS melanoma tumor cell line infected with NDV-ulster, as compared to co-culture with uninfected SMS cells." (PMID 37974615, 2023).